MUC20-OT1 (MUC20 overlapping transcript)
Synonyms: MUCP1; SDHAL2; SDHALP2; SDHAP2
Gene: Long non-coding RNA gene on chromosome 3 (195,635,709 to 195,739,964, forward strand). Ensembl gene ENSG00000242086.
Gene Ontology:
Biological process: SRP-dependent cotranslational protein targeting to membrane, signal sequence recognition
Cellular component: signal recognition particle, endoplasmic reticulum targeting